ALCAM (activated leukocyte cell adhesion molecule)
Diseases named in the same sentence as ALCAM in open-access papers (continued):
Sharing a sentence is not in itself a finding about the gene and the disease.
cancer (continued). "This article summarises recent findings and progress in ALCAM and its involvement in cancer, with a primary focus on its clinical connections and therapeutic values." (PMID 34680335, 2021). "The present article overviews the recent findings and progress in ALCAM and its involvement in cancer, with a primary focus on its clinical connections in cancer and therapeutic values." (PMID 34680335, 2021). "The present article aims to summarise the key findings of ALCAM in the area of cancer and will focus on the clinical, prognostic, and therapeutic aspects of ALCAM in cancer." (PMID 34680335, 2021). "Given the implications of ALCAM in cancer biology and its role as an adhesion molecule, investigations have focused on its clinical usefulness and importance in metastatic progression." (PMID 34680335, 2021). "The change of cellular fraction of ALCAM in cancer is intriguing, and its biological and clinical impact is yet to be fully understood." (PMID 34680335, 2021). "ALCAM (activated leukocyte cell adhesion molecule) is an important regulator in human cancers, particularly solid tumours." (PMID 34680335, 2021). "The previous sections have outlined the significant implications of ALCAM in clinical cancer and its relation to patient outcomes and prognosis." (PMID 34680335, 2021). "Cancer cell adhesion requires expression of cognate ligands and receptors on cancer and endothelial cells, notably integrins, collagens, selectins, and Activated Leukocyte Cell Adhesion Molecule (ALCAM)." (PMID 34641959, 2021). "As a type 1 transmembrane glycoprotein of the immunoglobulin superfamily, ALCAM functions as a cell surface sensor and promoter of interactions between cancer and endothelial cells." (PMID 34641959, 2021). "In vitro and in vivo studies have demonstrated that ALCAM is involved in migration, invasion, and stemness in several cancers." (PMID 33270750, 2020). "ALCAM has been increasingly used as a biomarker for the diagnosis, treatment response, and survival prediction in various cancers." (PMID 32460901, 2020). "The upregulation of ALCAM mediated by miR-214 plays a key role in the metastasis and proliferation of cancer cells." (PMID 31959866, 2020). "ALCAM has been shown to be a prognostic marker in several types of cancers; however, it is both a marker of good and poor prognosis depending on the cancer type." (PMID 33270750, 2020). "In fact, ALCAM is known to be expressed in the cytoplasm of many carcinomas and the pattern of expression seems to vary depending on the particular carcinoma." (PMID 33270750, 2020). "Differential expression of ALCAM has been observed in many other cancer types, where its cellular location again has been implicated as a significant factor." (PMID 31695844, 2019). "In our current study ALCAM-Fc chimera also had differential effects on cancer cell attachment to endothelial or osteoblast cells, inhibiting LNCaP but not PC-3 or VCaP cell attachment." (PMID 31695844, 2019). "Upregulation of the metabolic genes (ALDH18A1, CAD, CHKA, POLD4, PSPH, and SQLE) and aberrant expression of cancer-related genes (ALCAM, ITGA6, DDIT3, MAP3K6, and PAK1) were found in mouse fed with high-fat-high-cholesterol similar to human NASH-HCCs." (PMID 31795276, 2019). "The cell adhesion molecule ALCAM has been recognized as an important molecule in cancer progression and metastasis though its precise role appears to be complex and remains to be fully elucidated." (PMID 31695844, 2019). "Similar observations regarding ALCAMs role in regulating cellular phenotype have been noted in a number of other studies/cancers, though others suggest a contrasting role for ALCAM in regulating such traits in vitro and in vivo." (PMID 31695844, 2019). "Assessment of known cell stemness biomarkers DPP4, CD44, MSI1 and ALCAM as well as autofluorescence showed that resistant cells are enriched with cancer stem cells." (PMID 31336714, 2019).
cancer (continued). "Work from our laboratory and that of others has demonstrated that the level of shed ALCAM in biofluids is elevated in a variety of cancer patients, suggesting that ALCAM shedding increases during oncogenesis and malignant progression." (PMID 29453336, 2018). "We demonstrated for the first time the aberrant expression of cancer-related genes (ALCAM, ITGA6, DDIT3, MAP3K6 and PAK1) and metabolism-related genes (ALDH18A1, CAD, CHKA, POLD4, PSPH, SQLE and CFD) in human NASH-HCCs." (PMID 30367044, 2018). "Again, these data suggest that the effects of alternative splicing of ALCAM on cell-cell cohesion persist across multiple cancer cell types." (PMID 29453336, 2018). "In cancer, ALCAM has emerged as a significant factor in disease progression; however, the relationship between the expression of ALCAM and its correlation with aggressive disease has been debated." (PMID 29453336, 2018). "The measurement of ALCAM expression should serve as a potential index of cancer-specific survival rates of patients with GCTB." (PMID 29463803, 2018). "While broadly applicable in the field of cell adhesion, our findings highlight the importance of regulating ALCAM shedding in cancer." (PMID 29453336, 2018). "GCTB stromal cells exhibit cancer stem-like cells features and ALCAM is expressed on the cell surface of a putative cancer stem-like cells sub-population of stromal cells of GCTB." (PMID 29463803, 2018). "In recent years, alterations in ALCAM expression have been reported in various malignancies, such as melanoma, cancer in lung, esophagus, colon, pancreas, prostate, bladder, ovary, and breast." (PMID 29315254, 2018). "Urinary ALCAM levels were also measured for patients with inflammatory diseases or other cancers to confirm that the significant elevation of urine ALCAM was specific to the presence of BCa." (PMID 27894096, 2017). "ALCAM, as a member of the ‘immunoglobulin super family’, is known to be involved in cancer cell proliferation and migration." (PMID 29375378, 2017). "This is the first study to provide a multi-level assessment of ALCAM prognostication in cancer and definitively show that it is post-translational processing of ALCAM, defined as ALCAM “shedding”, that is most predictive of patient outcome." (PMID 27894096, 2017). "It was found that decreased ALCAM expression (IRS <8) in nodal metastases shows a trend related with a correlation with shorter cancer specific overall survival (P = 0.083)." (PMID 26134500, 2015). "In cancer cells internalization of ALCAM seems to be necessary for rearrangement of cell–cell contacts since the maximum of internalized ALCAM has been observed at the cleavage furrow during cytokinesis." (PMID 26703751, 2015). "It was also found that decreased ALCAM expression (IRS <8) in nodal metastases shows a trend related with a correlation with shorter cancer specific overall survival (P = 0.083)." (PMID 26134500, 2015). "This aspect is also especially very interesting in cancer cells since ALCAM has been suggested to play a crucial role in cancer progression." (PMID 26703751, 2015). "ALCAM is emerging as an important molecule in cancer due to its consistent differentiation of aggressive phenotypes, prognosis and response to therapy." (PMID 25255861, 2014). "Recombinant sALCAM chimeric molecules inhibit the adhesive function of CD166/ALCAM through a competitive binding effect, which results in increased cancer cell motility." (PMID 23940674, 2013). "Prior studies in other cancer entities have reported that ALCAM is upregulated in some and downregulated in others." (PMID 22475274, 2012). "ALCAM expression has been described in subsets of cells being involved in dynamic growth and migration but it has also been detected in cancer stem cells." (PMID 22475274, 2012). "Existing reports are paradoxical, with ALCAM gene expression being highly upregulated in some cancers and greatly downregulated in others." (PMID 22745734, 2012).
cancer (continued). "In some cancers ALCAM has a prognostic value or is predictive for the benefit of therapeutic interventions." (PMID 22475274, 2012). "Taken together, our data confirm the relevance of ALCAM as an important predictor for clinical outcome in cancer." (PMID 19603023, 2009). "Thus, ALCAM has been identified as a potential therapeutic target through monoclonal antibody or specific chimeric antigen receptor T-cell (CAR-T cell) cancer treatment." (PMID 38560563, 2024). "Furthermore, ALCAM expression has been proposed as a valuable prognostic marker in several types of cancer." (PMID 38542421, 2024). "Therefore, targeting ALCAM represents a novel therapeutic opportunity in both preventing and treating peritoneal metastases in gastric, pancreatic and other cancers." (PMID 36614319, 2023). "Previous studies have focused on the therapeutic implications of ALCAM in various cancer types." (PMID 36614319, 2023). "It has been well demonstrated that ALCAM on cancer cells and ALCAM on endothelial cells can trigger ALCAM-ALCAM mediated cancer-endothelial interactions and lead to cancer cells’ clustering over the endothelium layer, thus orchestrating the extravasation process." (PMID 36614319, 2023). "In addition, cancer cells of gastric and pancreatic origins were used to create cell models with decreased or increased levels of ALCAM expression by genetic knocking down or overexpression, respectively." (PMID 36614319, 2023). "Contributing to potential migratory capacity might be enhanced expression of ALCAM, which is involved in cancer cell migration, in conjunction with the activation of the EMT pathway." (PMID 38003292, 2023). "ALCAM has been reported to link with the progression of various cancers." (PMID 37705744, 2023). "Finally, the present study has shown that the ‘seed’ and ‘soil’ interaction between cancer cells and the mesothelial cells is primarily mediated by ALCAM." (PMID 36614319, 2023). "Use of ALCAM targeted therapeutics for cancer might raise issues of off target consequences related to widespread expression of ALCAM on other cell types including many types of cells of the immune system." (PMID 36275816, 2022). "In addition, as an adhesion molecule, ALCAM also involved in migratory and adhesive properties, played roles in cancer metastasis and leukocyte homing." (PMID 36482940, 2022). "A suitable reason for this is the contrasting role of ALCAM in cancer; for example, it may affect the growth and colony formation on the one hand but affecting migration and metastasis in an opposite way." (PMID 34680335, 2021). "While the current review focuses strongly on the impact of ALCAM in clinical cancer." (PMID 34680335, 2021). "The role of ALCAM in cancer cells has been an interesting topic of debate." (PMID 34680335, 2021). "The finding that ALCAM is a suitable indicator for patients’ response to drug treatment is very interesting, although the finding has so far been limited to a small number of cancer types." (PMID 34680335, 2021). "On the other hand, soluble ALCAM (truncated ALCAM) is also an option to explore in these cancers." (PMID 34680335, 2021). "Thus, the expression and the pattern of expression of ALCAM in cancer have an important bearing on the function of cancer cells." (PMID 34680335, 2021). "In addition, we observed upregulation of several collagens, integrins and other cell adhesion molecules, including FN1 and ALCAM, suggesting modulation of adhesive properties in cancer cells upon flow exposure." (PMID 34641959, 2021). "Therefore, the impact of ALCAM expression on prognosis seems to depend on the cancer type, and in some types of cancer, membranous versus cytoplasmic ALCAM expression should also be considered." (PMID 33270750, 2020). "Notably, our results are consistent with those from previous reports regarding other carcinomas in which depletion of ALCAM suppresses cell proliferation and migration in vitro, but the cells demonstrate invasiveness in vivo." (PMID 33270750, 2020).
cancer (continued). "Accumulating evidence suggests that ALCAM may play a role in cancer cell dissemination and development within the bone environment." (PMID 31695844, 2019). "Thus, we suggest that differential splice isoform expression provides an explanation for increased ALCAM shedding in patients with cancer and provides a mechanism by which ALCAM detected in biofluids is prognostic of poor outcome." (PMID 29453336, 2018). "In cancer, detecting the ALCAM shedding, as well as the switch from ALCAM-Iso1 to ALCAM-Iso2 may function as an indicator of disease progression." (PMID 29453336, 2018). "Therapeutic targeting of alternative splicing in cancer is an active field of research; therefore, identifying the regulatory mechanisms guiding alternative splicing in ALCAM could potentially lead to novel cancer therapies." (PMID 29453336, 2018). "Thus, we aimed to elucidate the intrinsic regulatory mechanisms controlling ALCAM shedding in cancer progression." (PMID 29453336, 2018). "Also, ALCAM expression has been reported in prostate, breast, ovarian, pancreatic, and colorectal cancers." (PMID 28537909, 2017). "In vivo mouse studies suggest a role of ALCAM in cancer progression." (PMID 26703751, 2015). "In this review, we will describe in more detail the cell adhesion molecules NCAM, L1, MCAM and ALCAM since they play a role in the nervous system and in cancer and have been described to be ubiquitinated and discuss possible roles of this posttranslational modification." (PMID 26703751, 2015). "Additionally, enhanced intensity of immunohistochemical reaction related with ALCAM detection shows a trend related with a correlation with cancer recurrence (P = 0.082)." (PMID 26134500, 2015). "However, depending on the original tissue of the cancer cells ALCAM becomes either upregulated or downregulated compared to healthy tissue, complicating the understanding of its role in cancer." (PMID 26703751, 2015). "However, our results as well as other studies are conflicting if taking into account that reduced expression of ALCAM has also been related to poor survival in some types of cancer." (PMID 19603023, 2009). "CD9 is also shown to associate directly with ADAM17 on the surface of different cell types (cis interactions), including leukocytes and cancer cells, and through this association exerts an inhibitory effect on ADAM17 sheddase activity against its substrates, including TNFα, ICAM-1 or ALCAM." (PMID 38542421, 2024). "Thus, in this rich ‘soil’ for cancer metastases, it is quite possible that the ALCAM-ALCAM interaction between cancer and mesothelium may make ALCAM act as both a ‘seed’ receptor of cancer cells and a ‘soil’ receptor for the mesothelium." (PMID 36614319, 2023). "However, it is likely that other cell adhesion molecules on the surface of the cancer cells and mesothelial cells may contribute to this interaction as a maximum effect by blocking ALCAM, by way of sALCAM and by genetic ALCAM knockdown are up to 60%." (PMID 36614319, 2023). "However, little is known whether ALCAM has a role in the peritoneal metastasis by mediating the interaction between cancer cells and peritoneal mesothelial cells." (PMID 36614319, 2023). "The results of these experiments established that ALCAM is also involved in the adhesion of Colo-320 cells to immobilized EVs, providing support for a more general role of this adhesion molecule in the interactions between cancer cells and EVs derived from them." (PMID 35628559, 2022). "the recognition that ALCAM may serve as a pivotal receptor for a cancer cell to seek its metastatic destination places it as an important player in the ‘seed and soil’ theory of cancer metastasis proposed more than a century ago." (PMID 36482887, 2022). "Taken together, ALCAM expression appears to be useful as a predictive prognosis tool, however, some contrast appears within the literature and its role may be dependent on cellular localization or cancer type." (PMID 31695844, 2019).
cancer (continued). "Interestingly, in cancer cells internalization of ALCAM happens much more slowly than in neurons." (PMID 26703751, 2015). "Collectively these data suggest that the ALCAM relocalization from the cell membrane to cytoplasm might ultimately enhance the migratory properties of malignant cells facilitating metastatic dissemination in several cancers." (PMID 21364949, 2011). "ALCAM (activated leukocyte cell adhesion molecule), also known as CD166, plays a crucial role in mediating the adhesion of cancer cells." (PMID 40118855, 2025). "The heatmap reveals significant differences in the signaling of ICAM, ALCAM, PVR, IL1, and CD137 emitted by VPS25high and VPS25low cancer cells." (PMID 40149859, 2025). "The dysregulation of cell migration, adhesion and invasion regulators, such as MCAM/CD146, ALCAM/CD166, CAR/CXADR, EFNA1, LAMA5, CD73/NT5E and integrins, contributes to cancer progression and metastasis." (PMID 40314078, 2025). "ALCAM also called CD166, is a pivotal cell adhesion protein mediating migration, growth, and adhesiveness in cancer cells involving NF-κB, β-catenin, and Twist signaling, as well as has complicated clinical prognostic significance in different cancers." (PMID 37701037, 2023). "Of particular interest was the finding that CD6-CAR T cells also showed potent cytotoxic responses against human CRC cancer stem cells, which exhibit robust CD166/ALCAM expression." (PMID 38139340, 2023). "Importantly, when ALCAM were knocked down from both cancer cells and mesothelial cells, the interaction between the two cell types were greatly reduced compared to an individual knocking down, further supporting the role of ALCAM in both “seed” and “soil” receptors during the process of metastasis." (PMID 36614319, 2023). "CD24, CD133, CD166 (ALCAM), CD44, EpCAM, CD29, Lgr5, ALDH1B1, and ALDH1A1 are some of the cytoplasmic and surface markers which have been utilized to detect putative cancer CSCs." (PMID 38202898, 2023). "However, ALCAM expression is not always linked to bad prognosis in cancer." (PMID 36275816, 2022). "All lines tested expressed moderate to high levels of CD166/ALCAM, a ligand of CD6 that is found on activated leukocytes, cancer cells, and many normal tissue cell populations." (PMID 33497367, 2021). "The expressions of cell adhesion molecules, especially ALCAM (activated leukocyte cell adhesion molecule) and ICAM1 (intercellular adhesion molecule 1), which have been reported to play vital roles in cancer cell adhesion, were remarkably downregulated." (PMID 33809909, 2021). "Activated leukocyte cell adhesion molecule (CD166; ALCAM) is an immunoglobulin-family receptor expressed on activated leukocytes and in some cancers." (PMID 28521775, 2017). "Among these candidates, six genes (RhoGDI1, ALCAM, FOXJ2, FOXO3, NDRG2 and SOX11) were involved in the suppression of cancer metastasis." (PMID 26460549, 2015). "CD166, also known as activated leukocyte cell adhesion molecule (ALCAM), is expressed by various cells in several tissues including cancer." (PMID 25221999, 2014). "Activated leukocyte cell adhesion molecule (ALCAM, CD166) is expressed in various tissues, cancers, and cancer-initiating cells." (PMID 21364949, 2011). "ALCAM (known also as CD166) is a cell surface adhesion glycoprotein related to immunoglobulins that modulates cell–cell interactions and is found at sites of cell–cell junction, with an important role in cancer progression and metastasis." (PMID 37685904, 2023). "CD166 (activated leukocyte cell adhesion molecule, ALCAM), is a transmembrane glycoprotein belonging to the immunoglobulin superfamily that was demonstrated to be overexpressed in various cancers." (PMID 38201468, 2023). "β integrins expressed on the surface of cells lacking ALCAM expression can mediate the binding and uptake of cancer-derived EVs lacking ALCAM through their interactions with specific EV ligands, such as the ADAM17 or fibronectin." (PMID 35628559, 2022).